LAMB1 (laminin subunit beta 1)
Description:
Binding to cells via a high affinity receptor, laminin is thought to mediate the attachment, migration and organization of cells into tissues during embryonic development by interacting with other extracellular matrix components. Involved in the organization of the laminar architecture of the cerebral cortex. It is probably required for the integrity of the basement membrane/glia limitans that serves as an anchor point for the endfeet of radial glial cells and as a physical barrier to migrating neurons (By similarity). Radial glial cells play a central role in cerebral cortical development, where they act both as the proliferative unit of the cerebral cortex and a scaffold for neurons migrating toward the pial surface (By similarity). As a subunit of laminin-1 (also known as laminin-111 or EHS laminin), it is involved in the stimulation of agrin-induced receptor clustering through a MuSK-independent pathway (By similarity).
Synonyms: CLM; LIS5; LKBMH; LUCAO
Tractability: Antibody: its Gene Ontology location is reachable by antibodies, with high confidence; UniProt places it where antibodies can reach, with medium confidence; UniProt predicts a signal peptide or a membrane-spanning region. PROTAC: ubiquitination databases record sites on it; its protein half-life has been measured. Other modalities: an approved drug acts on it.
Gene: Protein-coding gene on chromosome 7 (107,923,715 to 108,004,434, reverse strand). Ensembl gene ENSG00000091136.
Subcellular location: Secreted, extracellular space, extracellular matrix, basement membrane
Pathways (Reactome):
Extracellular matrix organization: Degradation of the extracellular matrix; ECM proteoglycans; Formation of the dystrophin-glycoprotein complex (DGC); Laminin interactions; Non-integrin membrane-ECM interactions
Developmental Biology: Developmental Lineage of Pancreatic Ductal Cells; EGR2 and SOX10-mediated initiation of Schwann cell myelination; L1CAM interactions
Metabolism of proteins: Post-translational protein phosphorylation; Regulation of Insulin-like Growth Factor (IGF) transport and uptake by Insulin-like Growth Factor Binding Proteins (IGFBPs)
Disease: Attachment of bacteria to epithelial cells
Signal Transduction: MET activates PTK2 signaling
Gene Ontology:
Molecular function: extracellular matrix structural constituent; protein binding; receptor ligand activity; structural molecule activity; enzyme binding; glycosphingolipid binding; integrin binding
Biological process: endodermal cell differentiation; neuron projection development; neuronal-glial interaction involved in cerebral cortex radial glia guided migration; odontogenesis; positive regulation of cell migration; substrate adhesion-dependent cell spreading; cell adhesion; positive regulation of cell adhesion; positive regulation of epithelial cell proliferation; positive regulation of integrin-mediated signaling pathway; positive regulation of muscle cell differentiation; positive regulation of skeletal muscle acetylcholine-gated channel clustering; regulation of basement membrane organization; regulation of cell adhesion; regulation of cell migration; regulation of embryonic development; negative regulation of cell adhesion; signal transduction
Cellular component: basement membrane; extracellular exosome; extracellular matrix; extracellular region; laminin-1 complex; laminin-10 complex; laminin-2 complex; laminin-8 complex; endoplasmic reticulum lumen; laminin-12 complex; laminin-6 complex; perinuclear region of cytoplasm; protein complex involved in cell-matrix adhesion; cytoplasm; laminin complex; nucleus
Genetic constraint (gnomAD): Loss-of-function variants: 109 observed, 212.61 expected, observed/expected ratio (o/e) 0.51, 90% interval 0.44 to 0.6. The upper end of that interval is the gene's LOEUF score, 0.6, which puts it in group 2 of 6, group 1 being the genes least tolerant of losing a copy. Missense variants: 2,085 observed, 2,233.3 expected, observed/expected ratio (o/e) 0.93, 90% interval 0.9 to 0.97. Synonymous variants: 763 observed, 815.3 expected, observed/expected ratio (o/e) 0.94, 90% interval 0.88 to 0.99.
Gene-disease validity (ClinGen):
ClinGen rates the evidence that LAMB1 causes each of these diseases.
cobblestone lissencephaly without muscular or ocular involvement (autosomal recessive): Moderate. Cobblestone lissencephaly without muscular or ocular involvement is a form of cobblestone lissencephaly characterized by a constellation of brain malformations which can either exist alone or in conjunction with minimal muscular and ocular abnormalities.
Homologues: Orthologues: macaque LAMB1 (99% identical), chimpanzee LAMB1 (97% identical), pig LAMB1 (94% identical), mouse Lamb1 (93% identical), dog LAMB1 (93% identical), rat Lamb1 (93% identical), guinea pig LAMB1 (91% identical), rabbit LAMB1 (91% identical), tropical clawed frog lamb1 (72% identical), zebrafish lamb1a (67% identical), zebrafish lamb1b (55% identical). Paralogues in human: LAMB2 (50% identical), LAMB4 (41% identical), LAMA2 (23% identical), LAMA5 (23% identical), LAMA1 (23% identical), LAMA3 (22% identical), LAMB3 (21% identical), LAMC1 (21% identical), LAMC3 (20% identical), USH2A (20% identical), HSPG2 (18% identical), AGRN (15% identical), and 15 more.
Diseases named in the same sentence as LAMB1 in open-access papers:
LAMB1 is named in the same sentence as 91 diseases in open-access papers, as found by Europe PMC text mining. Sharing a sentence is not in itself a finding about the gene and the disease. The quoted sentences say what the papers report.
colorectal cancer (7 papers, 2020 to 2025). A primary or metastatic malignant neoplasm that affects the colon or rectum. "Changes in LAMB1 levels in the sera of patients with colorectal cancer may therefore be a novel putative diagnostic biomarker for colorectal cancer." (PMID 36984512, 2023). "Of note, LAMB1, a carcinoembryonic antigen maker for colorectal cancer, exhibited a 6.95-fold increase." (PMID 39866228, 2025). "LAMB1 levels are high in the serum of colorectal cancer patients, so LAMB1 can be used as a potential serological biomarker." (PMID 33435161, 2021). "LAMB1 has also been shown to be a potential biomarker for some cancers, such as colorectal cancer and multiple myeloma." (PMID 33777800, 2021). "Colorectal cancer patients have been found to exhibit elevated level of LAMB1 in their serum, suggesting that LAMB1 could act as a potential serum marker." (PMID 39874810, 2025). "Furthermore, LAMB1 was significantly associated with OS and DSS respectively in AML, DLCBL, glioma, NSCLC, colorectal cancer and colorectal cancer, breast cancer." (PMID 32581652, 2020). "We then assessed the role of LAMC1 and LAMB1 in H-1PV cellular uptake in two other cancer cell lines, namely HCT116 (colorectal carcinoma) and A549 (lung adenocarcinoma)." (PMID 34158478, 2021).
breast cancer (6 papers, 2012 to 2023). A primary or metastatic malignant neoplasm involving the breast. "LAMB1 is overexpressed in capillary BMs in breast tumor tissues, which is associated with breast cancer progression and metastasis." (PMID 37140985, 2023). "KYNU, CTSD and PMP22 are known to be up‐regulated in advanced metastatic cancers and correlate with poor prognosis whereas LAMB1 encodes a laminin‐1 protein shown to have reduced expression in breast cancer." (PMID 25241147, 2015). "LAMB1 is highly expressed in most cancers while low in some cancers including breast cancer, leukemia, ovarian cancer and prostate cancer." (PMID 32581652, 2020). "A previous study reported that overexpression of LAMB1 is associated with both poor OS and DFS in breast cancer." (PMID 28544536, 2017). "We have previously examined three laminin subunit genes (LAMA1, LAMA2, and LAMB1), the promoter regions of which undergo abnormal methylation in breast cancer (BC) at frequencies higher than 16%5." (PMID 33500458, 2021). "One gene, LAMB1, was common to both OS and DFS gene sets, suggesting that this gene may be related to not only the sensitivity to the adjuvant therapy, but also to the malignant potential of the breast cancer cells." (PMID 28544536, 2017).
gastric cancer (6 papers, 2020 to 2025). A primary or metastatic malignant neoplasm involving the stomach. "LAMB1 was also found to be associated with poor prognosis in patients with gastric cancer." (PMID 33435161, 2021). "Its involvement in cancer is multifaceted, previous studies have linked DDX24 to liver cancer progression through stabilization of LAMB1 mRNA 39-40, and gastric cancer growth." (PMID 39897555, 2025). "Studies have shown that LAMB1 is significantly expressed in multiple invasive cancers and plays a significant role in cancer progression, as observed in gastric cancer, and lung adenocarcinoma." (PMID 39199357, 2024). "Examination of LAMB1 expression in six patients with normal and tumor tissues for gastric cancer showed an increase in the expression of LAMB1 in tumor than normal tissues." (PMID 33435161, 2021). "We found that the ERK pathway regulates LAMB1 expression levels in gastric cancer, demonstrating the regulation of LAMB1 via the ERK pathway, thereby inducing cancer cell growth and motility." (PMID 33435161, 2021). "To identify the effect of the ERK pathway on LAMB1 expression in gastric cancer, we treated AGS and MKN-28 cells with the ERK pathway inhibitor, U0126." (PMID 33435161, 2021). "In this study, we showed that ERK/c-Jun regulates LAMB1 expression and that LAMB1 is a potential therapeutic target for developing the treatment of gastric cancer." (PMID 33435161, 2021). "Knockdown of LAMB1 in vitro inhibited cancer cell growth and motility, whereas overexpression of LAMB1 significantly enhanced cell proliferation, invasion, and migration of gastric cancer cells." (PMID 33435161, 2021). "We showed that LAMB1 is upregulated at both gene and protein expression levels in gastric cancer tissues and cell lines." (PMID 33435161, 2021). "U0126, an extracellular signal-regulated kinase (ERK) inhibitor, regulated the expression of LAMB1 in gastric cancer cells." (PMID 33435161, 2021). "In this study, public datasets have demonstrated that overexpression of LAMB1 in gastric cancer promotes tumor growth and is a marker of poor prognosis." (PMID 33435161, 2021). "Here, we determined that LAMB1 is upregulated in gastric cancer tissues and contributes to cell growth and motility." (PMID 33435161, 2021). "In this study, we demonstrate that LAMB1 expression is elevated in gastric cancer patients and that LAMB1 influences cell growth and motility in gastric cancer." (PMID 33435161, 2021). "We reconfirmed the mRNA expression of LAMB1 using the publicly available GEO datasets of gastric cancer patients, which indicated significant overexpression of LAMB1 in gastric cancer." (PMID 33435161, 2021). "Kaplan–Meier analysis showed that overexpression of LAMB1 was associated with poor overall survival (OS), first progression (FP), and post-progression survival (PPS) of gastric cancer patients." (PMID 33435161, 2021). "The transcriptional activation of LAMB1 by c-Jun in gastric cancer, which needs to be explored further." (PMID 33435161, 2021). "Using a public database, we showed that LAMB1 expression was significantly upregulated in gastric cancer compared to normal tissues." (PMID 33435161, 2021). "Overexpression of LAMB1 elevated cell proliferation, invasion, and migration; however, knockdown of LAMB1 decreased these effects in gastric cancer cells." (PMID 33435161, 2021). "Inhibition of the ERK pathway is also a potential therapeutic target marker in gastric cancer with LAMB1 overexpression." (PMID 33435161, 2021). "Both mRNA and protein expression levels of LAMB1 we upregulated in all gastric cancer cells, except in SNU-601 cells." (PMID 33435161, 2021). "To investigate the biological role of LAMB1 in gastric cancer, we generated AGS and MNN-28 cells for the knockdown of LAMB1 using designed siRNAs." (PMID 33435161, 2021). "LAMB1 is upregulated in gastric cancer and promotes tumor development through the ERK/c-Jun axis." (PMID 36299585, 2022).
gastric cancer (continued). "We focused on identifying a transcription factor regulating LAMB1 expression in gastric cancer." (PMID 33435161, 2021). "In addition, we found that c-Jun can bind LAMB1 promoter regions and function as a transcription factor to regulate LAMB1 gene expression in gastric cancer, which needs to be explored further to elucidate its function." (PMID 33435161, 2021). "To determine whether LAMB1 expression influences cell motility during invasion and migration in gastric cancer, we showed that LAMB1 knockdown decreased cell invasion and migration in AGS and MKN-28 cells using Transwell assay." (PMID 33435161, 2021). "Our results revealed that LAMB1 is significantly overexpressed in gastric cancer tissues and exerts the biological function of promoting tumor growth and cell invasion and migration of gastric cancer cells." (PMID 33435161, 2021). "We believe that the overexpression of LAMB1 may induce laminin overexpression, thereby mediating cancer progression and metastasis, and can serve as a critical biomarker of gastric cancer." (PMID 33435161, 2021). "We focused on LAMB1 as a potential biomarker and its cellular mechanisms in gastric cancer." (PMID 33435161, 2021). "We hypothesized that LAMB1 might be involved in the oncogenic function and cell motility of invasion and migration of gastric cancer cells." (PMID 33435161, 2021). "We also investigated LAMB1 expression in gastric cancer patient tissues." (PMID 33435161, 2021). "In this study, we aimed to explore the effects of LAMB1 in gastric cancer." (PMID 33435161, 2021). "We confirmed LAMB1 expression in normal gastric cancer cells and six gastric cancer cell lines." (PMID 33435161, 2021). "ChIP assays showed that c-Jun directly binds to LAMB1 promoter in gastric cancer cells." (PMID 33435161, 2021). "However, the function and mechanism of LAMB1 remain undefined in gastric cancer." (PMID 33435161, 2021). "Finally, we investigated the mechanism of LAMB1 function and revealed that it could serve as a potential biomarker and therapeutic target of gastric cancer." (PMID 33435161, 2021). "Moreover, we need to identify in the further study whether LAMB1 promotes the secretion and expression of laminin 111 in gastric cancer." (PMID 33435161, 2021). "Moreover, to determine whether knockdown of c-Jun inhibited the mRNA and protein expression of LAMB1 in gastric cancer, we treated AGS and MKN-28 cells with JUN-specific siRNAs and found that c-Jun knockdown decreased LAMB1 expression at both mRNA and protein levels in AGS and MKN-28 cells." (PMID 33435161, 2021). "However, the role and mechanism of LAMB1 in gastric cancer remains unknown." (PMID 33435161, 2021). "LAMB1 overexpression in gastric cancer cells was examined in SNU-601 and SNU-668 cells transfected with mock vector or LAMB1 overexpression vector." (PMID 33435161, 2021). "Moreover, ERK/c-Jun/LAMB1 pathway may serve as a novel therapeutic target in gastric cancer." (PMID 33435161, 2021). "Therefore, our study indicates that LAMB1 promotes cell growth and motility via the ERK/c-Jun axis and is a potential biomarker and therapeutic target of gastric cancer." (PMID 33435161, 2021). "Additionally, we showed that c-Jun directly binds to the LAMB1 promoter as a transcription factor and regulates its gene expression via the ERK pathway in gastric cancer cells." (PMID 33435161, 2021). "However, the transcriptional role of c-Jun in regulating LAMB1 gene expression in gastric cancer has not been studied yet." (PMID 33435161, 2021).
hepatocellular carcinoma (6 papers, 2020 to 2025). A malignant tumor that arises from hepatocytes. "Moreover, hepatocellular carcinoma (HCC) exhibited an upregulation of LAMB1, which was associated with heightened tumor aggressiveness and unfavorable patient survival." (PMID 38239636, 2023). "LAMB1 is upregulated in hepatocellular carcinoma tissues and its co-expression with keratin-19 leads to poor prognosis and shortened survival in these patients." (PMID 36984512, 2023). "Together these findings suggest that regulated IRES-dependent translation of LamB1 is an important factor for the control of EMT in hepatocellular carcinoma." (PMID 32517298, 2020). "Stabilized LAMB1 by RNA helicase DDX24 promotes hepatocellular carcinoma progression." (PMID 39866228, 2025). "LamB1 regulates the laminin-mediated integrin signaling that promotes cell adhesion, motility and differentiation by acting as a ligand of the monomeric laminin receptor, which drives tumor cell invasion in hepatocellular carcinoma." (PMID 32517298, 2020). "This increased LamB1 translation results in upregulation of laminin-mediated integrin signaling through binding of LamB1 to the laminin and β1 integrin receptors, which were both found to be overexpressed in hepatocellular carcinoma, thereby leading to tumor cell invasion." (PMID 32517298, 2020). "Co-treatment with KPA also decreased the expression of genes, regulating the progression of fibrosis (e.g., COL6A3, AEBP1, SPARC, TNC, LAMB1, BGN) and hepatocellular carcinoma (e.g., COL4A1, COL4A2, TUFT1, VCAN, NID1)." (PMID 39404414, 2024). "In hepatocellular carcinoma (HCC), LAMB1 expression increases tumor progression during invasion via PDGF/La axis-mediated LAMB1 translation." (PMID 33435161, 2021). "In hepatocellular carcinoma (HCC), LAMB1 is known to upregulate cell signaling via the ERK and Akt pathways." (PMID 33435161, 2021). "During hepatocellular carcinoma EMT, La accumulates in the cytoplasm where it binds to the LamB1 IRES to enhance IRES-mediated translation." (PMID 32517298, 2020).
glioma (5 papers, 2020 to 2024). A benign or malignant brain and spinal cord tumor that arises from glial cells (astrocytes, oligodendrocytes, ependymal cells). "Restoring miR-124-5p expression inhibited glioma growth by suppressing angiogenesis, similar to the effects observed upon LAMB1 knockdown." (PMID 39485747, 2024). "It is known from previous studies that miR-124-5p inhibits the growth of high-grade gliomas through posttranscriptional regulation of LAMB1." (PMID 32220226, 2020). "LAMB1 has a high protein level in high-grade gliomas, suggesting a possible correlation with tumor progression." (PMID 32581652, 2020). "Further, antisense oligonucleotides against laminin-8 (LAMA4 and LAMB1) were found to block the invasion of glioma cells and neovascularization in vitro." (PMID 32571313, 2020).
colon cancer (4 papers, 2019 to 2024). "One study showed increased blood levels of LAMB1 in colon cancer patients relative to controls, highlighting its potential biomarker properties." (PMID 35323693, 2022). "It has been reported that the transcription factor of the AP-1 complex binds and regulates LAMB1 gene expression upon binding to its promoter in F9 mouse embryonal cells and LAMC2 in HT29 human colon cancer cells." (PMID 33435161, 2021). "In primary colon cancer and liver metastasis resection specimens, LAMA5 and LAMB1 were strongly expressed within the vascular basement membrane where they encased the tumour vasculature similar to the pattern in the orthotopic tumours." (PMID 31064120, 2019). "In support of the increased cancer-specific production of these laminin chains, we identified significantly greater expression of LAMA5, LAMB1 and LAMC1 transcripts in colon cancer tissues compared with normal colon in publicly available gene array data using the OncomineTM platform." (PMID 31064120, 2019). "Among others, human LAMA5, LAMB1 and LAMC1 transcripts were expressed at high levels, with little or no expression of human collagen IV identified, indicating that the laminins required for vascular basement membrane assembly are produced by metastatic colon cancer cells." (PMID 31064120, 2019).